Y_RNA (Y RNA )
Gene: Miscellaneous RNA gene on chromosome 9 (41,672,295 to 41,672,406, reverse strand). Ensembl gene ENSG00000278028.
Homologues: Paralogues in human: Y_RNA (99% identical), Y_RNA (98% identical), Y_RNA (97% identical), Y_RNA (96% identical), Y_RNA (94% identical), Y_RNA (87% identical), RNY1P5 (86% identical), Y_RNA (86% identical), Y_RNA (85% identical), Y_RNA (84% identical), Y_RNA (83% identical), RNY1 (82% identical), and 100 more.